RNU7-53P (RNA, U7 small nuclear 53 pseudogene)
Synonyms: U7.53
Gene: Small nuclear RNA gene on chromosome 5 (130,386,621 to 130,386,680, reverse strand). Ensembl gene ENSG00000252514.
Homologues: Orthologues: macaque U7 (95% identical), pig U7 (83% identical). Paralogues in human: RNU7-24P (87% identical), RNU7-61P (87% identical), RNU7-21P (85% identical), RNU7-35P (85% identical), RNU7-48P (85% identical), RNU7-52P (85% identical), RNU7-62P (85% identical), RNU7-7P (85% identical), RNU7-20P (83% identical), RNU7-25P (83% identical), RNU7-2P (83% identical), RNU7-37P (83% identical), and 142 more.